LRPPRC (leucine rich pentatricopeptide repeat containing)
Diseases named in the same sentence as LRPPRC in open-access papers (continued):
Sharing a sentence is not in itself a finding about the gene and the disease.
Alzheimer disease (1 paper, 2025). A progressive, neurodegenerative disease characterized by loss of function and death of nerve cells in several areas of the brain leading to loss of cognitive function such as memory and language. "It has been reported that the reduction of LRPPRC expression is implicated in many human diseases, such as Alzheimer's disease and Parkinson's disease, and the KEGG analysis also identified these pathways which were affected significantly by T-96 in this study." (PMID 39744573, 2025).
basal cell carcinoma (1 paper, 2023). A carcinoma involving the basal cells. "Through OCLR algorithm, it can be seen that mRNAsi, EREG-MRNASI value has significant difference between the two clusters (p < 0.05), suggesting that FMR1, LRPPRC, RBMX, YTHDC2 and IGF2BP1 may affect CRC by regulating the pathway of basal cell carcinoma." (PMID 37194014, 2023).
cardiomyopathy (1 paper, 2021). A disease of the heart muscle or myocardium proper. "The regulatory roles of other enriched genes in cardiomyopathy networks (including SYNE2, APOB, XIRP1, ALPK3, and LRPPRC) are not clear." (PMID 34236536, 2021).
Cognitive impairment (1 paper, 2026). Abnormal cognition is characterized by deficits in thinking, reasoning, or remembering. "Notably, a novel short peptide designed to competitively inhibit LRPPRC K223 lactylation remarkably ameliorates cognitive impairment in diabetic mice." (PMID 41942754, 2026).
colitis (1 paper, 2024). Inflammation of the colon. "We further tested the mRNA and protein levels of the characterized genes in the intestinal mucosa of DSS-induced colitis mice and UC patients, and the results showed that the mRNA and protein levels of SLC7A11, NDUFS1, LRPPRC, and CD2AP were dramatically downregulated in DSS-induced colitis mice." (PMID 38977802, 2024).
colorectal cancer (1 paper, 2023). A primary or metastatic malignant neoplasm that affects the colon or rectum. "The signature might provide five candidate targets (RBMX, FMR1, IGF2BP1, LRPPRC, YTHDC2) associated with specific clinical features, prognosis and improvement in immunotherapy for patients with colorectal cancer." (PMID 37194014, 2023). "To clarify the role of RBMX, FMR1, IGF2BP1, LRPPRC and YTHDC2, we analyzed the mRNA expression patterns in human colorectal cancer specimens." (PMID 37194014, 2023).
COVID-19 (1 paper, 2024). A disease caused by infection with severe acute respiratory syndrome coronavirus 2. "RNA export adapter proteins such as LRPPRC or ELAVL1 also function as readers of RNA N6-methyladenosine modification (m6A), which is crucial for the transmission and pathogenicity of COVID-19." (PMID 38674024, 2024).
depression (1 paper, 2022). "Next, we performed differential gene analysis of m6A regulators in depression and found that FTO, RBM15B, METTL3, LRPPRC, HNRNPC, ZC3H13, and YTHDF2 were significantly upregulated in depressed rats." (PMID 35480327, 2022).
diabetic kidney disease (1 paper, 2025). Progressive kidney disorder caused by vascular damage to the glomerular capillaries, in patients with diabetes mellitus. "LRPPRC was broadly expressed across all renal cell types and was downregulated in patients with diabetic kidney disease." (PMID 40255566, 2025).
Dyskinesia (1 paper, 2020). A movement disorder which consists of effects including diminished voluntary movements and the presence of involuntary movements. "Mitochondrial susceptibility in the putamen is reported to play a role in the development of dyskinesia in patients with PD, suggesting that abnormal energy metabolism caused by LRPPRC variants may be associated with the occurrence of LID." (PMID 32733355, 2020).
Encephalopathy (1 paper, 2020). Encephalopathy is a term that means brain disease, damage, or malfunction. "We first characterized the clinical and molecular features of a novel LRPPRC variant in a male Sicilian child with early onset encephalopathy and psychomotor impairment." (PMID 32972427, 2020).
HIV-1 infection (1 paper, 2012). The type species of lentivirus and the etiologic agent of acquired immunodeficiency syndrome (AIDS). "Combined these data indicated that LRPPRC depletion affects the early events of HIV-1 infection by at least two mechanisms." (PMID 22808186, 2012). "Finally, the loss of mitochondrial LRPPRC may also contribute to the reduction of HIV-1 infection." (PMID 22808186, 2012). "To test if LRPPRC was necessary for HIV-1 infection we measured the transduction of a HIV-1 virus engineered to express luciferase (HIV-Luc) into the LRPPRC-depleted cell lines." (PMID 22808186, 2012). "HIV-1 infection was reduced in all three cell lines, but virus production and RNA encapsidation were unaffected, suggesting that LRPPRC was critical for the afferent stage of virus replication." (PMID 22808186, 2012). "To investigate the requirement of LRPPRC for HIV-1 infection, we constructed 293T cell lines stably depleted of LRPPRC by short hairpin RNA (shRNA) interference." (PMID 22808186, 2012). "Stable knockdown of LRPPRC with three independent shRNAs reduced HIV-1 infection during the early phase of virus replication." (PMID 22808186, 2012). "PCR analysis of the early steps of HIV-1 infection determined that LRPPRC knockdown led to a reduction in nuclear import of vDNA and reduced PIC formation." (PMID 22808186, 2012). "The other ascribed functions of LRPPRC provide additional means through which its depletion could impact HIV-1 infection." (PMID 22808186, 2012). "Thus LRPPRC reduction could negatively impact HIV-1 infection by altering mitochondrial health and reducing the function of critical metabolic pathways to a level that does not support efficient virus replication." (PMID 22808186, 2012). "Immunoprecipitation of Flag-LRPPRC specifically captured HIV-1 viral RNA and viral DNA in early HIV-1 infection." (PMID 22808186, 2012). "The stable knockdown of LRPPRC in 293T cells resulted in delayed cell growth compared to cells expressing a non-specific shRNA, suggesting a possible mechanism for the impact of LRPPRC expression on MLV and HIV-1 infection." (PMID 22808186, 2012).
Hypertension (1 paper, 2026). The presence of chronic increased pressure in the systemic arterial system. "However, we identified novel genes (SBF2, ARHGAP12, EPAS1, CLEC16A, and LRPPRC) to be associated with hypertension." (PMID 41898884, 2026).
ischemia (1 paper, 2023). A hypoperfusion of the BLOOD through an organ or tissue caused by a PATHOLOGIC CONSTRICTION or obstruction of its BLOOD VESSELS, or an absence of BLOOD CIRCULATION. "In addition, qRT-PCR and Western blotting also confirmed that the expression of METTL16 and LRPPRC was downregulated and the expression of RBM15 was upregulated after ischemia." (PMID 37139237, 2023).
Leukoencephalopathy (1 paper, 2015). This term describes abnormality of the white matter of the cerebrum resulting from damage to the myelin sheaths of nerve cells. "Three of the patients (Patients 2, 8 and 10) also demonstrated striking symmetrical leukoencephalopathy with avid restricted diffusion, a feature not previously documented in cases with LRPPRC mutation." (PMID 26510951, 2015).
lymph node metastases (1 paper, 2014). "Univariate analysis shows that the following factors were significantly related to postoperative survival: depth (P = 0.004), lymph node metastasis (P = 0.007), distant metastasis (P < 0.001), TNM stage (P = 0.004), and LRPPRC expression (P < 0.001)." (PMID 24375316, 2014).
neurofibromatosis type 1 (1 paper, 2021). A clinically heterogeneous, neurocutaneous genetic disorder characterized by cafe-au-lait spots, iris Lisch nodules, axillary and inguinal freckling, and multiple neurofibromas. "Loss or mutation of LRPPRC may contribute to manifestations of neurofibromatosis type 1, which has characteristics of cognitive dysfunction." (PMID 34461609, 2021).
osteoarthritis (1 paper, 2023). A noninflammatory degenerative joint disease occurring chiefly in older persons, characterized by degeneration of the articular cartilage, hypertrophy of bone at the margins and changes in the synovial membrane. "Among them, VIRMA and LRPPRC were the most highly correlated m6A regulators expressed in all samples and osteoarthritis samples and showed a positive correlation, whereas VIRMA and RBM15B were the most negatively correlated." (PMID 36777725, 2023).
osteomyelitis (1 paper, 2022). An acute or chronic inflammation of the bone and its structures due to infection with pyogenic bacteria. "In the m6A regulators-associated molecular subtypes, METTL3, CBLL1 and LRPPRC were significantly more highly expressed in subgroup A osteomyelitis than in subgroup B, while RBM15B and YTHDC1 expression were higher in subgroup A osteomyelitis." (PMID 36544487, 2022). "Furthermore, METTL3 and LRPPRC were determined to be closely associated with immune infiltration by immune infiltration analysis, which will provide guidance for personalized immunotherapy of osteomyelitis patients in the future." (PMID 36544487, 2022). "Among the 6 m6A regulators, METTL3 and LRPPRC were highly expressed in subgroup A osteomyelitis, whereas YTHDC1 was highly expressed in gene cluster B osteomyelitis." (PMID 36544487, 2022). "Among them, two m6A regulators (METTL3 and LRPPRC) were closely related to immune infiltration in patients with osteomyelitis." (PMID 36544487, 2022). "Visualization of the results by boxplot and heatmap suggested that the 5 regulators were differentially expressed between the two m6A subtypes, with METTL3, CBLL1 and LRPPRC highly expressed in cluster A osteomyelitis, RBM15B and YTHDC1 highly expressed in cluster B osteomyelitis." (PMID 36544487, 2022). "The qRT‒PCR results showed that the mRNA expression of METTL3, YTHDC1, RBM15B, LRPPRC and CBLL1 in osteomyelitis tissues was significantly increased, while that of YTHDF2 was significantly decreased (p < 0.05), which was consistent with the results of bioinformatics analysis." (PMID 36544487, 2022). "Based on the 6 significant m6A regulators with differential expression in the dataset, we further validated the expression of the 6 m6A regulators (METTL3, YTHDC1, YTHDF2, RBM15B, LRPPRC and CBLL1) in 10 osteomyelitis samples and 10 control samples by qRT‒PCR analysis." (PMID 36544487, 2022).
osteosarcoma (1 paper, 2023). A usually aggressive malignant bone-forming mesenchymal neoplasm, predominantly affecting adolescents and young adults. "Nevertheless, the intricate pathways and effects of LRPPRC, along with associated DRGs, on osteosarcoma progression and immune cell infiltration remain enigmatic and warrant deeper investigation." (PMID 37892851, 2023). "In conclusion, our study introduces and validates a unique prognostic signature based on two DRGs (MYH9 and LRPPRC) for osteosarcoma." (PMID 37892851, 2023). "In summary, we assume that LRPPRC may potentially promote the progression of osteosarcoma by exerting immunosuppressive effects." (PMID 37892851, 2023).
Ovarian Tumors (1 paper, 2025). "Our in vivo data demonstrated that pharmacological blocking of LRPPRC’s function results in a long-term therapeutic benefit and can be an effective therapy in SDHA- and LRPPRC-overexpressing ovarian tumors." (PMID 40563592, 2025). "Importantly, our in vivo data showed that pharmacological inhibition of LRPPRC results in a lasting therapeutic benefit and can be an effective therapy in SDHA- and LRPPRC-overexpressing ovarian tumors." (PMID 40563592, 2025).
Primary amenorrhea (1 paper, 2020). "POI-24 carried c.7G > T and c.2965C > T bi-allelic mutations in LRPPRC and suffered from primary amenorrhea." (PMID 32962729, 2020).
prostate adenocarcinoma (1 paper, 2014). "Recently, we found that elevated levels of LRPPRC in prostate adenocarcinomas are closely associated with poor prognosis of prostate cancer patients." (PMID 24722279, 2014). "Therefore, patients at late stage of prostate adenocarcinomas exhibit higher levels of LRPPRC than those at early stage of the disease." (PMID 24722279, 2014).
pulmonary arterial hypertension (1 paper, 2025). Pulmonary arterial hypertension (PAH) is a group of diseases characterized by mean pulmonary artery pressure >20 mmHg and elevated pulmonary arterial resistance leading to right heart failure. "Dysregulation of the LRPPRC-m6A-CENPF regulatory axis could acceleratecellular senescence via genomic instability pathways, linking to the cancer-likepathological mechanisms observed in pulmonary arterial hypertension." (PMID 40521894, 2025).
retinoblastoma (1 paper, 2025). A malignant tumor that originates in the nuclear layer of the retina. "It has been reported that LRPPRC promotes retinoblastoma progression and glycolysis by targeting HIF-1α, which is corroborates with our results." (PMID 40775462, 2025).
staphylococcus aureus infection (1 paper, 2021). An infectious process in which the bacteria Staphylococcus aureus is present. "Our results implied that patients in the low-LRPPRC enriched genes of mRNA processing, RNA splicing and mRNA processing, and patients in the high-LRPPRC enriched genes of Staphylococcus aureus infection, hematopoietic cell lineage and complement and coagulation cascades." (PMID 34650549, 2021).
triple-negative breast carcinoma (1 paper, 2025). An invasive breast carcinoma which is negative for expression of estrogen receptor (ER), progesterone receptor (PR), and human epidermal growth factor receptor 2 (HER2). "For example, in triple-negative breast cancer (TNBC), it was found that LRPPRC could bind to the m6A-modified mRNA of lactate dehydrogenase A (LDHA)." (PMID 40555877, 2025).
uterine corpus endometrial carcinoma (1 paper, 2024). A endometrial carcinoma (disease) that involves the body of uterus. "To ascertain the role of LRPPRC in the tumor microenvironment and progression of uterine corpus endometrial carcinoma, we initially examined LRPPRC’s involvement in the TME of UCEC patients by leveraging GO pathways." (PMID 39445012, 2024).
ZIKV infection (1 paper, 2022). "AaVA-1 is a crucial target that promotes DENV and ZIKV infection in vitro in human THP-1 cells and in vivo in mouse models via interaction with human leucine-rich pentatricopeptide repeat-containing protein (LRPPRC)." (PMID 36070318, 2022).
tumor (71 papers, 2014 to 2026). "In recent years, overexpressed LRPPRC emerged as a potent tumor oncogene linked with poor patient prognosis in various human cancers." (PMID 40563592, 2025). "We also showed that LRPPRC enhanced proliferation, invasion, and migration in OV cells, whereas LRPPRC overexpression rescued the tumor inhibitory effect caused by HAPSTR1 loss-of-function." (PMID 38643468, 2024). "Of note, the gene LRPPRC, known as Leucine Rich Pentatricopeptide Repeat Containing, was specifically linked to the advancement of tumor grade and stage." (PMID 39445012, 2024). "It was found that overexpression of LRPPRC gene was detected in various human malignancies, and overexpression of LRPPRC gene was strongly associated with poor prognosis of tumor patients." (PMID 37399661, 2023). "High LRPPRC expression was associated with poor clinical outcomes (HR = 1.98, P = 0.0043) and tumor stage in patients with OC." (PMID 37496051, 2023). "Above data preliminarily proved that LRPPRC was negatively associated with anti-tumor immunity and immune infiltration in HCC." (PMID 37063837, 2023). "In conclusion, we identify a SNHG17/LRPPRC/c-Myc regulatory axis and characterize its function in G1/S transition, which uncovers new mechanisms underlying cell proliferation and tumor growth, and provides potential targets for anti-cancer therapy." (PMID 34671012, 2021). "LRPPRC encodes a nuclear protein that is significantly negatively correlated with the immune response in a variety of tumour tissues 59-61." (PMID 34512165, 2021). "It was observed that LRPPRC-deficient group exhibited the lower tumor weight." (PMID 37063837, 2023). "In addition, Ki-67–positive tumor cells displayed the remarkable reduction in LRPPRC-deficient group." (PMID 37063837, 2023). "Altogether, LRPPRC deficiency strengthened anti-tumor immunity and immune infiltration in vivo." (PMID 37063837, 2023). "Taken together, SNHG17 may inhibit c-Myc ubiquitination and thus stabilize c-Myc protein by associating with LRPPRC, which leads to upregulation of c-Myc, acceleration of G1/S transition and cell proliferation, and consequent tumor growth." (PMID 34671012, 2021). "Targeting OXPHOS through Leucine-Rich PPR Motif-Containing Protein (LRPPRC) degrader-mediated OXPHOS Complex Biogenesis Inhibition (OCBI) has demonstrated promising anti-tumor activity." (PMID 41901318, 2026). "Previous studies have shown that LRPPRC can not only stabilize and translate the mRNA of complex IV, thereby affecting oxidative phosphorylation in tumor cells." (PMID 41516324, 2025). "Among these LRPPRC, a potential oncogene in multiple tumour types, detected at both RNA and protein level, which plays a role in mitochondria homeostasis." (PMID 40022181, 2025). "The LRPPRC protein emerged as a tumor oncogene with a central role in mitochondrial homeostasis and energy metabolism." (PMID 40563592, 2025). "This suggests that SDHA-overexpressing cancer cells are particularly vulnerable to the LRPPRC inhibition, which leads to tumor cell death." (PMID 40563592, 2025). "IHC staining showed that the expression level of Ki‐67 and WDR76 was decreased in xenograft tumours induced by LRPPRC knockdown in MDA‐MB‐231 cells, while the inhibitor of glutaminase BPTES further lowered the level of Ki‐67." (PMID 38372449, 2024). "The injection of LRPPRC‐overexpressing BT549 cells greatly increased the ability of TNBC cells to develop secondary tumours in the lung, and this effect was attenuated by FX‐11." (PMID 38372449, 2024). "We found that the expression of LRPPRC was significantly higher in UCEC malignant tumor cells compared to other cells." (PMID 39445012, 2024). "In contrast, injection of LRPPRC knockdown MDA‐MB‐231 cells substantially impaired the ability of TNBC cells to form secondary tumours in the lung, and LRPPRC knockdown plus BPTES accelerated this reduction." (PMID 38372449, 2024).